VIM (vimentin)
Diseases named in the same sentence as VIM in open-access papers (continued):
Sharing a sentence is not in itself a finding about the gene and the disease.
prostate carcinoma (209 papers, 1994 to 2025). A carcinoma that arises from epithelial cells of the prostate gland. "Elevated vimentin expression has been associated with metastatic potential and poor prognosis in various cancer types, including liver, breast, lung, and prostate cancers." (PMID 39851801, 2025). "Previous studies investigating the impact of vimentin expression find that overexpression is associated with metastatic disease and poor prognosis in liver, breast, lung, and prostate cancers." (PMID 39516342, 2024). "Activation of this pathway increased EMT markers (E-cadherin and Vimentin) in prostate cancer cells, leading to the loss of adhesion and the acquisition of invasion and migration ability to promote prostate cancer." (PMID 37497001, 2023). "Overexpression of these sORFs-encoded peptides (miPEP200a and miPEP200b) in prostate cancer cells inhibits their migration by downregulating vimentin expression." (PMID 33810468, 2021). "Recent studies have revealed that vimentin expression is linked with motile prostate cancer cell lines, and its knockdown significantly decreases tumor cell motility and invasive activity." (PMID 33919917, 2021). "Here, we found a positive significant association between 18F–choline uptake and the number of vimentin-positive prostate cancer cells." (PMID 31614564, 2019). "It has also been reported that cucurbitacin E exhibits specific cytotoxicity against prostate carcinoma explants, and the mechanism underlying this process is to induce disruption of the action and vimentin cytoskeleton in prostate carcinoma cells." (PMID 28708122, 2017). "Independent studies showed that metformin inhibited TGF-beta-stimulated loss of E-cadherin and gain of vimentin as well the decrease of N-cadherin and prostate cancer cell motility." (PMID 28977822, 2017). "High vimentin expression has been reported in bone metastasis of prostate cancer and has been implicated in prostate cancer cell invasion." (PMID 25887999, 2015). "Specifically, over-expression of PDGF-D caused EMT phenotype in PC3 prostate cancer cells with loss or relocation of E-cadherin and increased expression of Vimentin and Nestin, suggesting that PDGF-D overexpression contributes to EMT in human cancers." (PMID 24158561, 2013). "For summary, many of the core aPKC regulatory functions of prostate carcinoma cells PC-3 and DU-145 could be regulated by association with and consequent phosphorylation of vimentin both in-vitro and in-vivo." (PMID 33525953, 2021). "Vimentin-deficient cells also show defects in cell motility and directionality as well as a reduction in wound healing capacity while overexpression of vimentin promotes prostate cancer cell invasion and metastasis." (PMID 31569795, 2019). "VIM is a cytoskeletal protein which overexpression is known to be associated with aggressive disease and worse outcomes in solid cancers such breast, gastrointestinal, and prostate cancers." (PMID 29925392, 2018). "In the present study, we found that IL–20 regulated EMT-associated markers (E-cadherin, N-cadherin, vimentin, and fibronectin), affected prostate cell migration, and increased anchorage-independent growth in prostate cancer by inducing the phosphorylation of p38, ERK1/2, AKT, and NF-κB signals." (PMID 26440411, 2015). "Vimentin has been previously linked to the metastatic potential of cancer cells as its increased expression has been demonstrated to be a marker of epithelial-mesenchymal transition (EMT) in prostate cancer." (PMID 24212937, 2011). "TGF-β induces the EMT in prostate cancer in vitro via the suppression of E-cadherin levels, and elevates the expression of fibronectin, vimentin, and EMT-TFs such as ZEB1 and SNAI1/2." (PMID 39941895, 2025). "Previous studies have shown that estrogen can promote EMT through the estrogen receptor, downregulating E-cadherin and upregulating Snail and vimentin in breast and prostate cancer cells." (PMID 41228249, 2025).
prostate carcinoma (continued). "The negative influence of miR-216a-5p on EMT has already been described in prostate cancer, where the overexpression of the miRNA reduced N-cadherin, Vimentin, and Snail levels." (PMID 40243417, 2025). "MALAT1 overexpression was closely linked to epithelial-mesenchymal transition (EMT), as evidenced by decreased E-cadherin and increased vimentin expression in colorectal, breast, and prostate cancers." (PMID 40674376, 2025). "Altered expression of integrin adhesion receptors and mesenchymal intermediate filaments, such as vimentin, are also important features of prostate cancer cells undergoing EMT and can potentiate cell migration to facilitate metastasis." (PMID 39796673, 2024). "LNCaP, PacMetUT1, and DU145 prostate cancer cells exposed to obese sera resulted in increased invasion and migration, showing increased vimentin." (PMID 38999849, 2024). "Treatment of Tan in prostate cancer PC-3 cells leads to suppressed EMT by attenuating Vimentin expression and increasing E-cad level through the PI3K/Akt/mTOR pathway." (PMID 38924029, 2024). "In the study, it was discovered that CALR can regulate the invasion and migration of prostate cancer cells, and can regulate mitochondrial membrane potential, calcium ion level, and ER stress, and the expression of Vimentin." (PMID 39479348, 2024). "In prostate cancer, vimentin expression was mainly detected in poorly differentiated tumors and metastatic lesions." (PMID 37717112, 2023). "In contrast to previous investigations in colorectal and prostate cancer cells 19, Vimentin was inhibited after NDRG1 silencing in MDA-MB-231 and MDA-MB-436 cells treated with TGFβ1, which was not seen in SUM159 and BT549." (PMID 36594086, 2023). "High expression of VIM is often detected in poorly differentiated prostate cancers and bone metastases." (PMID 37196186, 2023). "Prostate cancer progression increases the mesenchymal markers N-cadherin and vimentin; N-cadherin promotes EMT via activation of the ErbB signaling pathway and enhances the migratory and invasive potential of cancer cells." (PMID 37345021, 2023). "Our findings showed that EpCAM antibodies were more effective in isolating CTCs from localized prostate cancer, whereas vimentin antibodies were more effective in advanced prostate cancer." (PMID 37345161, 2023). "Addition of 4OHT in the Snail-inducible LNCaP95 prostate cancer cell line leads to cell scattering and upregulation of the mesenchymal marker, vimentin." (PMID 37228586, 2023). "An increased epithelial phenotype has been observed in the MET prostate cancer model showing strong vimentin expression in the parental cell line, DU145, when compared to the metastatic variant DU145-LN4." (PMID 36362433, 2022). "Of note, in a mouse tumor xenograft model, SCAND1 overexpression significantly reduced Ki-67(+) and Vimentin(+) tumor cells and inhibited migration and lymph node metastasis of prostate cancer." (PMID 36552758, 2022). "TNC is also reported to be significantly expressed alongside FSP1, αSMA and vimentin, and positively correlates with poor survival in patients with prostate cancer." (PMID 36671452, 2022). "In human prostate cancer cells, vimentin is phosphorylated at Ser33, Ser39 and Ser56 by atypical PKCs at the cell front, leading to the local disassembly of vimentin IFs, lamellipodium formation and cell migration." (PMID 35990612, 2022). "Consistently, hybrid EMT of prostate cancer cells within a tumor organoid (tumoroid) was identified by the co-expression of epithelial (E-cadherin+ EpCAM+) and mesenchymal (Vimentin+) markers with enhanced stemness." (PMID 36552758, 2022). "miR-20b-5p suppressed migration and invasion of prostate cancer cells by increasing E-cadherin and decreasing vimentin." (PMID 36582800, 2022). "In prostate cancer, Vimentin, N-cadherin, and E-cadherin fluctuated in a manner suggesting the suppression of EMT via regulation of ADAM9." (PMID 35740916, 2022).
prostate carcinoma (continued). "VIM has been shown to promote metastatic spread in prostate cancer and plays a role in making tumour cells more invasive." (PMID 34206049, 2021). "Like miR-200a and miR-200b, miPEP-200a and b over-expression in prostate cancer cells inhibits migration of these cells by regulating the vimentin-mediated pathway, suggesting that the miPEP-coding function of pri-miRs is present in humans." (PMID 33892772, 2021). "Some researchers have found that down-regulation of ATG5 expression under hypoxic conditions can inhibit the expression of EMT markers N-cadherin and vimentin, thereby inducing malignant development of prostate cancer cells." (PMID 34636718, 2021). "Anthocyanin 3,5-diglucoside, the major phytochemical constituent of muscadine grape skin extract, due to its antioxidant potential, facilitated the MET process in prostate cancer cells characterized by re-expression of E-cadherin and reduced vimentin levels." (PMID 34572548, 2021). "VIM antisense RNA 1 (VIM-AS1) increases N-cadherin and vimentin while downregulating E-cadherin in promoting prostate cancer EMT." (PMID 33672595, 2021). "Myofibroblasts develop from their fibroblast precursors, and their phenotype is marked by the expression of vimentin, an intermediate filament that is upregulated in poorly differentiated prostate cancer and in bone metastases." (PMID 33672595, 2021). "We treated cell lines that represent benign prostate tissue and different prostate cancer types with IFN-γ and then evaluated the expression of the EMT markers N-cadherin, E-cadherin and vimentin to elucidate the underlying mechanism." (PMID 33692219, 2021). "Both aPKCs are upregulated simultaneously to facilitate EMT in tested prostate cancer cell lines to keep Vimentin dynamics in optimum conditions." (PMID 33525953, 2021). "Previous studies have demonstrated that up-regulation of miR-203 expression in prostate cancer cells results in up-regulation of E-cadherin and down-regulation of Vimentin, thereby inhibiting EMT transformation." (PMID 33109107, 2020). "In prostate cancer, vimentin is expressed in poorly differentiated cancers, but hardly detectable in highly differentiated or moderately differentiated tumors." (PMID 32670437, 2020). "Reduction TNAP by short hairpin RNA was reported significantly reduced prostate cancer cells migration with lower vimentin expression." (PMID 31969558, 2020). "CNTN1 increases tumor cell invasion, migration, and metastasis by promoting EMT via activation of the PI3K/AKT pathway, downregulation of E-cadherin, and upregulation of N-cadherin and vimentin in lung and prostate cancers." (PMID 33194679, 2020). "In regard to the marker of the EMT, linear regression, analyses showed a positive and significant correlation between the number of vimentin-positive prostate cancer cells and 18F–choline uptake evaluated in terms of SUV average (r2 = 0.2787; p < 0.0001)." (PMID 31614564, 2019). "Third, GA markedly increased the protein expression of two pro-proliferative cell cycle regulators, three EMT-TFs and vimentin, and decreased protein expression of E-cadherin in three prostate cancer cells." (PMID 31060254, 2019). "But in a recent publication, it was reported that PD-L1 expressed in the nucleus of vimentin-positive CTCs predicts poor prognosis in colorectal and prostate cancer patients." (PMID 31212653, 2019). "Vimentin overexpression has been reported in cancers of the prostate, gastrointestinal tract, breast and many others." (PMID 29925392, 2018). "Another possible treatment targets PKCε, as cell motility is promoted by phosphorylation of vimentin by PKCε, and genetic deletion of PKCε has been shown to inhibit development of prostate cancer in mouse model." (PMID 30248895, 2018). "Both vimentin and Slug were significantly increased in Jazf1-overexpressing prostate cancer cell lines." (PMID 29416651, 2018).
prostate carcinoma (continued). "TGF-beta induced EMT in prostate cancer cells, increasing E-cadherin, vimentin and Slug, effects mitigated by metformin." (PMID 28977822, 2017). "A transgenic mouse model of prostate cancer tumorigenesis and metastasis was paired with a vimentin‐GFP reporter to track the expression of this mesenchymal marker in prostate tumor cells." (PMID 28544498, 2017). "On the contrary, mesenchymal proteins such as Snail, α-SMA, and vimentin displayed positive relationships with malignant states of prostate cancers." (PMID 27926483, 2017). "This is highlighted by the findings that miR-17-3p inhibits the expression of vimentin in prostate cancer and that miR-17-3p expression in prostate cancer specimens and cell lines inversely correlates with aggressiveness." (PMID 29271928, 2017). "In this sense we recently reported a restrospective study where vimentin expression was analyzed in CTCs detected by the CellSearch technology in 142 samples of 93 patients with advanced prostate cancers." (PMID 27391263, 2016). "Here we report CTC expression of vimentin and Ki67 in advanced/metastatic prostate cancer, offering a clinical insight into their mesenchymal and proliferative properties." (PMID 26923772, 2016). "Increased vimentin expression has been reported in various tumor cell lines and tissues including prostate cancer." (PMID 26910370, 2016). "NF-κB was reported to mediate TGF-β1-induced vimentin which was identified as an independent predictor of prostate cancer recurrence." (PMID 27145282, 2016). "We analysed Ki67 and vimentin expression in CTC derived from a total of 144 advanced prostate cancer patients using CellSearch technology, optimized and validated to assay Ki67 and vimentin in separate patient cohorts." (PMID 26923772, 2016). "We have established a method for testing CTC expression of Ki67 and vimentin in the normal pathway of prostate cancer care." (PMID 26923772, 2016). "Migration inhibitory effects of miR-17-3p expression have been reported earlier in prostate cancer cells, which showed reduced vimentin expression upon of miR-17-3p overexpression." (PMID 27650539, 2016). "Previous studies in our group have shown that NF-κB is an essential downstream mediator of TGF-β-induced prostate cancer cell vimentin expression and EMT." (PMID 26317041, 2015). "The protein levels of these genes were significantly decreased in prostate cancer cells transfected with miR-195, except for vimentin and HMGA1." (PMID 26337460, 2015). "PC3 cells were firstly used to test the existence of EMT in prostate cancer cells by EpCAM, CK and Vimentin immunostaining." (PMID 26397728, 2015). "NF-κB and vimentin expression also correlated with increasing pathological grade and biochemical recurrence of clinical prostate cancer." (PMID 26317041, 2015). "In some carcinomas, including prostatic carcinoma, vimentin is overexpressed and is therefore a marker for invasiveness and metastasis." (PMID 26512779, 2015). "We observed a down-regulation in E-cadherin and an increased Snail and Vimentin expression in prostate cancer cells with estrogen treatment." (PMID 26575018, 2015). "With this method, we identified and sorted prostate cancer cells from a heterogeneous population by performing >132 000 simultaneous single-cell TaqMan RT-PCR reactions targeting vimentin mRNA." (PMID 25030902, 2014). "To demonstrate the utility of PACS-based TaqMan RT-PCR to identify specific cells in a heterogeneous population, we targeted expression of vimentin in DU145 prostate cancer cells spiked into Raji B-lymphocyte-derived cells." (PMID 25030902, 2014). "In prostate cancer, abrogating the expression of vimentin significantly decreases tumor cell invasiveness, an effect that has been attributed to its ability to regulate the E-cadherin/β-catenin complex via c-Src regulation." (PMID 24797520, 2014).
prostate carcinoma (continued). "We therefore conclude that a reduction in the levels of both plectin and vimentin produced by the cells resulted in suppressed cell invasion in the prostate cancer cell line." (PMID 23717685, 2013). "The differentially regulated proteins identified in the study, including plectin and vimentin, are discussed in the context of their significance to prostate cancer progression." (PMID 23717685, 2013). "The up-regulation of miR-143 in prostate cancer cells represses mesenchymal markers (vimentin and fibronectin) and increases the epithelial marker E-cadherin, while the up-regulation of miR-145 leads to the same effects except for vimentin." (PMID 22417299, 2012). "Confocal analysis of LNCaP, PC3 and DU145 prostate cancer cell lines (derived from lymph node, bone or brain prostate metastases, respectively) demonstrated that both domains of vimentin are present on the surface of these metastatic cancer cell types." (PMID 24212937, 2011). "We demonstrate that two different domains of vimentin are detectable on the surface for each of three commonly studied prostate cancer cell lines LNCaP, PC­3 and DU145." (PMID 24212937, 2011). "Our findings suggest the possibility of creating novel nanoparticle or antibody derivative constructs using vimentin as a way to target prostate cancer metastases and/or stem cells therapeutically." (PMID 24212937, 2011). "We suggest the potential utility of CPMV nanoparticle to target prostate cancers via vimentin interactions, this, however, requires formal testing." (PMID 24212937, 2011). "We were able to detect both qualitative and quantitative differences in the surface expression of vimentin between the three different prostate cancer lines." (PMID 24212937, 2011). "Increased vimentin expression has been indicated as an important step in epithelial-mesenchymal transition (EMT) required for the metastasis of prostate cancer." (PMID 24212937, 2011). "It is likely that surface vimentin can be targeted on metastatic prostate cancer cells by this nanoparticle." (PMID 24212937, 2011). "Proteome analysis indicated vimentin expression correlated with invasion and metastases of androgen-independent prostate cancers." (PMID 24212937, 2011). "In this report, we demonstrate for the first time that multiple epitope domains of vimentin are expressed on the surface of three different prostate cancer cell lines derived from three different metastatic tissue sites." (PMID 24212937, 2011). "A further understanding of the interplay between vimentin, vesicular trafficking machinery, and endosome transport could provide valuable insights into potential therapeutic targets that inhibit prostate cancer progression." (PMID 39796673, 2024). "Moreover, downregulation of GRP94 in prostate cancer cells can cause upregulation of cleaved caspase-9 and Bax expression levels, while suppression of Bcl-2 and Vimentin expression levels can induce apoptosis and inhibition of prostate cancer cell invasion." (PMID 38649679, 2024). "Likewise, vimentin is a well‐established mesenchymal–epithelial transition marker detected in metastases‐derived prostate cancer cells." (PMID 37644825, 2023). "Interestingly, combined engraftment of LNCaP human prostate cancer cells and vimentin+/αSMA+ CAFs in mice has also been shown to stimulate angiogenesis during early tumor progression." (PMID 36671452, 2022). "Indeed, inhibition of RHAMM using a mimetic peptide, P15-1, coincided with decreased myofibroblast differentiation and expression of mesenchymal markers such as vimentin and N-cadherin, resulting in decreased migration of fibroblast and prostate cancer cells." (PMID 36033439, 2022).